CD4 (CD4 molecule)
Diseases named in the same sentence as CD4 in open-access papers (continued):
Sharing a sentence is not in itself a finding about the gene and the disease.
viral infection (continued). "Moreover, consistent with prior work, we also observed more efficient viral infection, as measured by Gag-p24 expression, by DC-to-CD4 T cell trans-infection than from infection of CD4 T cells directly by free virus present in a supernatant (cis-infection) (p = 0.04)." (PMID 31398241, 2019). "The findings in the mice with genetical CD4 and/or CD8 deficiency supported the conclusion that the cellular inflammatory infiltration following viral infection in susceptible mouse strains contributes substantially to the mortality and myocardium lesion associated with viral infection." (PMID 29854842, 2018). "The most prominent example of the necessity of CD4 T cells in chronic viral infection stems from the LCMV system where depletion of CD4 T cells prior to infection results in persistent viremia compared to immunological control of the infection in the presence of CD4 T cells." (PMID 30453612, 2018). "Thus, during viral infections, CD4+ CTL may act in concert with cytolytic CD8+ T cells, bearing thus some advantages in terms of infection control." (PMID 28289418, 2017). "Although H3N2i vaccination induced protection preventing weight loss against homologous primary virus even in CD4 KO mice, H3N2i immune mice were not protective during heterosubtypic secondary virus infection at a later time despite significant viral replication during the first infection." (PMID 29276514, 2017). "Another example is the aryl hydrocarbon receptor (AHR), a regulator of mucosal barrier function, activation of which during lung development enhances CD4+ T-cell responses to viral infections, and which more generally may influence immune responsiveness in the lungs." (PMID 29262847, 2017). "In the case of protection from viral infection, CD4 CTLs may be specific for viral Ag(s), whereas in the case of inducing autoimmunity, such as in colitis or EAE, these cells could be specific for microbiota in the intestine or self Ag(s), such as myelin basic protein." (PMID 28280496, 2017). "Moreover, vaccine-induced CD107a+ CD4+ T cells are selectively depleted following virus infection." (PMID 28289418, 2017). "Infiltrating lymphocytes including natural killer (NK) cells, CD8+ T cells, CD4+ T cells, and B cells are often necessary for viral clearance from the brain, mediate recovery from multiple encephalitic virus infections and may protect against LACV-induced neuronal damage." (PMID 28340587, 2017). "Therefore, the reduced number of CD3+, CD4+, CD19+ T cells in patients with HCC to some extent indicates a decline in the body's antiviral ability, which ultimately contributes to the deterioration of diseases caused by persistent virus infection." (PMID 27813499, 2016). "Therefore, it will be useful to identify diterpene compounds suitable for HIV cure studies that could reactivate HIV from the latent reservoirs with low to minimal cytotoxicity while preventing new viral infections of CD4+ T cells." (PMID 26225771, 2015). "Therefore, massive activation of CD4+ T cells, which leads to more viral infection and cell death, might outrun the regeneration of T cells and cause progressive depletion." (PMID 26709961, 2015). "Furthermore, because CD4 T-cell depletion in HLACs is driven by cell death of abortively infected CD4 T cells, the data also suggest that IL-21 might broadly inhibit both productive and abortive viral infection by IL-21." (PMID 26108174, 2015). "The relatively high levels of expression of unphosphorylated endogenous SAMHD1 measured in memory CD4+ T lymphocytes suggested that SAMHD1 might significantly restrict viral infections in vivo, reduce virus production systemically, and affect disease progression if not adequately suppressed by Vpx." (PMID 25996507, 2015). "Interestingly, all pcTPANS1-inoculated mice depleted from CD4+ cells died after virus infection." (PMID 26650916, 2015).
viral infection (continued). "Thus, inflammatory signals induced by viral infection may overcome the need for strong IL-2 signals in driving cytotoxicity in CD4 cells." (PMID 24586481, 2014). "Thus, it seems that CD4+ T cell help is mandatory for CD8+ T cells to exploit their optimal effector function against persistent viral infections, which can be resolved only in the presence of both specific CD4+ and CD8+ T cells, as observed in the mouse model." (PMID 25166270, 2014). "Similarly, viral infection with CsA treatment resulted in an increase in CD4+ and CD8+ T cells that was, respectively, 9.3- and 7.8-fold higher when compared with mock-infected mice not treated with CsA, or was, respectively, 31.1- and 15-fold higher, compared to mock-infected/CsA-treated controls." (PMID 25121947, 2014). "Therefore, we next asked whether direct viral infection (as compared to exposure) would impact the ability of CD8αneg DCs to induce the proliferation of LCMV-specific CD4 or CD8 T cells." (PMID 24613988, 2014). "Indeed, it is well established that T cell mediated cytotoxicity effector function is associated with CD8+ T cell recognition of antigen presented by MHC Class I. However, recent studies suggest that CD4+ T cells may play a more direct role in viral infection." (PMID 24130479, 2013). "Although B cells can protect the host from viral infections by several mechanisms, including antigen presentation, cytokine production, and costimulation, the production of protective antibodies by B cells with the help from CD4+ T cells is generally thought to be critical." (PMID 23133489, 2012). "In order to distinguish the effects of viral infection from the normal variation of marker expression between donor tissues, for each matched tissue, we calculated the level of expression in infected (p24+) CD4 T cells as the percent of the level of expression in the matched non–infected tissue." (PMID 23236398, 2012). "Thus, it could be hypothesised that the degree of viral rebound may be related to the degree of immune reconstitution occurring during ART, or to the number of CD4 target cells available for viral infection at ART stop." (PMID 22952756, 2012). "Here, we focus on a structure that stabilizes Env in a conformation representative of its primary (CD4) receptor-bound state, thereby exposing highly conserved “CD4 induced” (CD4i) epitope(s) known to be important for co-receptor binding and subsequent virus infection." (PMID 22291921, 2012). "In general, these results demonstrate that these CD4+ T cell clones are cytotoxic in agreement with the view that CTL-mediated lysis of vaccinia virus may significantly contribute to the effect of the vaccine in controlling the virus infection with poxvirus." (PMID 21931646, 2011). "Foxp3+ CD4+ regulatory T cells represent a T cell subset with well-characterized immunosuppressive effects during immune homeostasis and chronic infections, and there is emerging evidence to suggest these cells temper pulmonary inflammation in response to acute viral infection." (PMID 22125630, 2011). "HSV-1-stimulated pDCs can downmodulate CD4 T cell activation directly through the production of IFN-I and IL-10, and indirectly through the induction of regulatory CD4 T cells, suggesting that pDCs may contribute to prevent excessive, detrimental, adaptive immune responses during viral infections." (PMID 21994554, 2009). "Based on our data, we propose that IL-10 produced upon FMDV infection suppresses CD4+ T cell activity, as we have previously shown during acute infection, promoting the activation of virus-specific B cells to produce neutralizing antibodies, clearing the viral infection." (PMID 19478852, 2009). "Therefore, it is necessary to assess whether a lower level of R88-A3G expression in CD4+ T cells renders cells resist to viral infection." (PMID 18414671, 2008).
viral infection (continued). "The proportion of CD4-TEMRA varies greatly across individuals and is positively correlated with a better clinical outcome in viral infections and vaccination." (PMID 41499515, 2026). "T-bet–expressing TH1 cells that secrete interferon-γ (IFN-γ) are known for their role in viral infections, and BCL-6 (B cell lymphoma 6)–expressing CD4+ TFH cells can secrete interleukin-21 (IL-21) and assist B cells." (PMID 41499515, 2026). "Functionally, CLOCKΔ19 produces β-catenin stabilization in T cells, pronounced expansion of RORγt+ CD4+ T cells and Treg cells, impaired Treg suppression of Th17 responses, heightened Th17 responses, and reduced IFN-γ production during viral infection." (PMID 41928813, 2026). "During fungal and viral infection, T-cell-intrinsic NRK1 maintains effector CD4+ T cell abundance within affected tissues and draining lymph nodes, supporting infection control." (PMID 41639086, 2026). "The ratios of CD4+ CD8+ (lymphocytes), CD11b+F480+ (neutrophil precursor), and CD11b+Ly6G+ (neutrophil) cells are significantly elevated after viral infection." (PMID 40590495, 2025). "Typically, CD8+ T cells are responsible for direct killing of infected cells, while CD4+ T cells predominantly augment CD8+ T cell functions and antibody responses during viral infections." (PMID 40476519, 2025). "In viral infections such as mpox, different T cell subsets secrete specific cytokines as part of the immune response: IFN-γ is mainly secreted by CD4+ Th1 cells and cytotoxic T cells, and IL-2 by CD4+ Th1 cells." (PMID 41012178, 2025). "Given that CD6 conversely supports CD4 T cell activation in many autoimmune models, we probed potential mechanisms of CD6-mediated suppression of CD4 T cell activation during viral infection." (PMID 39679790, 2025). "We first aimed to analyze the basic characteristics of virus infection and replication of varying HIV-1 strains in CD4+ T cells and macrophages." (PMID 40130873, 2025). "The first approach subdivides activated CD4+ T cells into CXCR6+CXCR5- Th1-like cells and CXCR6-CXCR5+ Tfh-like cells at the peak of immune response during viral infection." (PMID 40391228, 2025). "pDCs play a crucial role in controlling viral infection by secreting type 1 interferons and presenting antigens to CD8+ and CD4+ T cells." (PMID 40932794, 2025). "This is contrary to observations in viral infections, where CD8+ T cell depletion typically reduces immunopathology, and suggests a unique role of colonic CD4+ T cells in mucosal Salmonella infection." (PMID 40924026, 2025). "While P1 showed increased pS6 levels both in CD4+ and CD8+ T cells upon in vitro activation, P1’s mother harboring the same PIK3CD variant did not exhibit signs of PI3K hyperactivation, suggesting that the former maybe due to external factors such as recent or ongoing viral infection or similar." (PMID 41583441, 2025). "A decrease in LY count, particularly in CD4+ and CD8+ T-cell subsets, compromises the ability to clear viral infection and leads to dysregulated immune responses, resulting in persistent viral replication, cytokine overproduction, and tissue damage." (PMID 41327060, 2025). "Viral infections are frequent in elderly bronchiectasis patients with AEB and are characterized by reduced CD4+ T‐cell counts, lower CD4+/CD8+ ratios, and heightened inflammatory responses, reflecting underlying age‐related immune vulnerability." (PMID 41448851, 2025). "Consistent with CD8+ TM subsets, CD4+ TM cells can be traditionally categorized into CD62L+CCR7+ TCM cells, CD62L-CCR7- TEM cells, and CD69+ TRM cells under bacterial and viral infections." (PMID 40391228, 2025). "Recipient mice (Thy1.2+, also T-bet ZsGreen+ to prevent rejection) that had received naïve LCMV-specific (Smarta) CD4+ T cells from T-bet ZsGreen donors (Thy1.1+) were infected with LCMV Armstrong (Arm, 200 PFU) to elicit an acute viral infection." (PMID 41488650, 2025).
viral infection (continued). "This highlights the crucial roles that CD4+ and CD8+ T cells play in controlling viral infections in aging populations." (PMID 40732672, 2025). "Constitutive HIF-1 activity has been shown to potentiate effector functions in CD4+ and CD8+ T cells in tumor and viral infections." (PMID 40590226, 2025). "IFN-γ is primarily produced by T lymphocytes, particularly CD4+ and CD8+ T cells, as well as some natural killer (NK) cells upon viral infections." (PMID 40230837, 2025). "The reduction in B-lymphocytes (expressing Bu-1) and T-lymphocytes (expressing CD4 and CD45) resulted in viral infections at various time points." (PMID 40959137, 2025). "The NrHV mouse model represents a valuable model to investigate CD4-DC-CD8 interactions and LN versus hepatic CD8+ T cell priming during a true hepatic virus infection in vivo." (PMID 39392861, 2024). "CD3+ T lymphocytes with the CD4+ and CD8+ subpopulations are often involved in viral infections and genetically determined autoimmune diseases." (PMID 38611673, 2024). "HLA class I and II molecules play a significant role in shaping the host’s immune response to viral infections by serving as crucial proteins for presenting antigens to CD8+ and CD4+ T helper cells." (PMID 38785761, 2024). "Under conditions of prolonged chronic viral infections and sustained antigen exposure, LAG3 remains highly expressed on both CD4+ and CD8+ T cells, contributing to T cell exhaustion." (PMID 38592036, 2024). "Recent evidence highlights the potential role of CD4 CTL in controlling and protecting against viral diseases in pigs, particularly in the context of porcine respiratory and reproductive syndrome virus (PRRSV) infections." (PMID 38675825, 2024). "IFNγ can be secreted by innate lymphocyte cells, γδ T cells, and CD4+ and CD8+ T cells during viral infections." (PMID 38510965, 2024). "In recent years, there has been an increasing number of studies on CD4+/CD25+FoxP3+ regulatory T cells (Tregs) and their involvement in viral infections." (PMID 38979428, 2024). "Apolipoprotein A-I has been shown to limit cell fusion in HIV infected cells, in recombinant vaccinia virus infected CD4+ HeLa cells expressing HIV envelope protein, and herpes simplex virus all of which during viral infection decrease HDL levels." (PMID 38500508, 2024). "The ratio of CD4/CD8 is an important indicator of immune regulation, and its decrease indicates immune dysfunction, which is common in viral infection." (PMID 39495380, 2024). "The HPV vaccines induce a robust antibody response against oncogenic HPV vaccine types and stimulate interferon-γ producing CD4+ and CD8 + T lymphocytes, effective in clearing and preventing the viral infection." (PMID 39035570, 2024). "This strategy can potentially design CD4+ and CD8+ T-cell therapeutic candidates to combat persistent viral infections and develop versatile preventive vaccinations." (PMID 38629077, 2024). "CD4+ TEMRA cells, while clearly important in fighting viral infections, are also enriched in chronic inflammation and autoimmunity and are considered proinflammatory and cytotoxic but exhausted T cells." (PMID 39599626, 2024). "An increase in CCL5 levels in milk is expected because this chemokine is produced early during virus infection and can also be induced later in response to TNF-α and IFN-γ produced by CD4+ and CD8+ T cells, epithelial cells, fibroblasts, and platelets." (PMID 39867906, 2024). "An analysis of PBMC from patients with HCV revealed that specific CD4+ T lymphocytes indeed respond to stimulation with viral proteins and induce IFN-γ, TNF-α, and IL-2, the classic Th1 response expected in viral infections." (PMID 38690280, 2024). "Type II IFN (IFN-γ) is primarily produced by NK cells, Th1 CD4+ T cells, γδ-T cells, and CD8+ T cells upon viral infection and plays an important role in the combating of viral disease in both the periphery and the CNS." (PMID 38793662, 2024).
viral infection (continued). "We further included the analysis of peripheral CD45RAneg CD4+CXCR5+ CXCR3neg T follicular helper (Tfh) cells, since they produce large amounts of IL-21 cytokine to sustain both CD8 and B cell immunity during viral infections such as HIV-119,39,40." (PMID 39709477, 2024). "CD4+ cells are the primary cell fraction for acquired immunity, and memory CD8+ T cells are the principal component of immunity in the defense against viral infection." (PMID 38275805, 2024). "The inflammatory response triggered by viral infections plays a crucial role in the antiviral response, which is a process that involves the activation and proliferation of CD8+ T cells, CD4+ T cells, and dendritic cells." (PMID 38313434, 2023). "As major immune cells expressing CD4 and CCR5, albeit at lower levels than CD4+ T cells, they become crucial targets for viral infection in the CNS." (PMID 38060615, 2023). "For example, in asthmatic people, allergen-specific CD4+ TRM cells represent a dominant group residing in iBALT, and the bystander activation of these cells can occur when exposed to the viral infection." (PMID 36839573, 2023). "Higher CD4+ T-cell counts and lower HIV RNA levels at the time of immunisation correlate with a better immune response to the yellow fever vaccination." (PMID 37127045, 2023). "CD44-expressing CD4+ and CD8+ T cell populations were also expanded by SCFA treatment during viral infection." (PMID 37865711, 2023). "The molecular mechanism for how CD4+ T cells protect against CVB3 is unclear, but sex contributes to CD4+ T cell effector function during different diseases and viral infections." (PMID 38274806, 2023). "As many other viral infections, HCMV reactivations result in clonal expansion of CD4+ and CD8+ T cells." (PMID 37234158, 2023). "The study demonstrated that the identified CD4+ epitopes from the DENV-1 proteome can activate CD4+ T cells, which play a critical role in the adaptive immune response against viral infections." (PMID 37987878, 2023). "Overall, based on our collective data, we propose that while CD8+ T cells or CD4+ T cells alone are sufficient to control RSV infection, both are required for more rapid clearance of virus infection in vivo." (PMID 37159271, 2023). "Researchers have shown via fluorescence-activated cell sorting (FACS) analysis that patients with viral infections, especially those in intensive care units, had greater levels of PD-1 on both CD8+ T cells and CD4+ T cells." (PMID 36679947, 2023). "T cells with CD4 and CD8 markers are essential for controlling acute viral infection, while B lymphocytes produce antibodies specific to pathogens." (PMID 37576755, 2023). "CD4 T cell exhaustion has been well documented in CD4 T cell responses to viral infections, and the role of TCF-1 in regulating T cell exhaustion during viral infections is also clear." (PMID 36901757, 2023). "Adaptive immune cells, including CD4 T helper type 1 cells, γδT cells, activated NK cells, and cytotoxic CD8 T cells, secrete IFNγ upon viral infection." (PMID 37264110, 2023). "Acute SARS-CoV-2 infection resulted in rapid mitochondrial dysfunction in both CD4 and CD8 T cells, which compromised "T cell" functionality contributing to suppressed "T cell" immune responses to viral infection." (PMID 36821695, 2023). "B cells, CD4+ T cells, and CD8+ T cells are the three major adaptive immune cell types that control and clear viral infections." (PMID 37932287, 2023). "In addition, the combination of ribavirin and IFN-α in chronic HBV treatment was reported to induce the proliferation of CD4+ T cells that produce various signalling cytokines to initiate antiviral actions in infected cells and to alert neighbouring cells of the threatening virus infection." (PMID 37108513, 2023).